SMAD7 (SMAD family member 7)
Diseases named in the same sentence as SMAD7 in open-access papers (continued):
Sharing a sentence is not in itself a finding about the gene and the disease.
colitis (continued). "By using a mouse model of established colitis-driven intestinal fibrosis, we have recently shown that oral administration of Smad7 AS to colitic mice attenuated colitis thus limiting the degree of intestinal fibrosis." (PMID 36714553, 2023). "Oral administration of Smad7 AS to colitic mice reduced the degree of colitis and attenuated the degree of intestinal fibrosis." (PMID 33920230, 2021). "In a murine model of CAC induced by azoxymethane and DSS, Smad7 Tg mice develop a severe colitis characterized by a massive infiltration of the mucosa with CD8+ T cells and NKT cells and increased production of IFN-γ." (PMID 33920230, 2021). "Confirming this evidence, inhibiting Smad7 through the oral administration of Smad7 antisense oligonucleotide in vivo decreased inflammation in mice with colitis induced by haptenating reagents." (PMID 33670735, 2021). "TGF-β1/Smad3 signaling can be restored by treatment with a specific antisense oligonucleotide that specifically knocks down SMAD7 expression and inhibits the production of inflammatory cytokines, attenuating colitis in mice." (PMID 34059951, 2021). "On the other hand, transgenic over-expression of Smad7 in T cells exacerbates colitis in various mouse models of IBD." (PMID 33920230, 2021). "Consistently, DC-specific Smad7 deletion mitigated DSS-induced colitis by inducing CD103+PDL2/1+DC and Tregs." (PMID 33920230, 2021). "Consistently, Smad7 is over-expressed in mucosal tissues from patients with CMV-induced colitis and declines after antiviral ganciclovir therapy." (PMID 33920230, 2021). "Up-regulation of Smad7 also occurs in the colon of mice with oxazolone-induced colitis and mice with trinitrobenzene sulfonic acid (TNBS)-induced colitis, two animal models showing morphological and immunological similarities with UC and CD, respectively." (PMID 33920230, 2021). "Smad7 is over-expressed by tumoral cells in both sporadic CRC and colitis-associated CRC, where it sustains neoplastic processes through activation of either TGFβ-dependent or non-dependent pathways." (PMID 31052449, 2019). "This later result was consistent with data generated in mice with TNBS-mediated colitis-driven intestinal fibrosis, in which knockdown of Smad7 with the specific ASO reduced intestinal inflammation and fibrosis." (PMID 30983999, 2019). "Oral administration of Smad7 ASO to mice with TNBS and oxazolone-induced colitis restores TGF-β1-associated Smad signaling and mitigates intestinal inflammation." (PMID 30983999, 2019). "Following DSS administration, Smad7 Tg mice develop a more severe colitis and exhibit a further reduction of the number of Sirt1-positive T cells when compared with WT mice." (PMID 30147698, 2018). "We would like to point out that these findings do not exclude the possibility that additional factors other than Smad7 contribute to reduce the mucosal levels of Sirt1 during colitis." (PMID 30147698, 2018). "Colitic mice given oral Smad7 AS exhibit enhanced p-Smad3 expression, reduced expression of inflammatory cytokines and a less severe colitis." (PMID 29973939, 2018). "Since high Smad7 contributes to amplify inflammatory signals in experimental models of colitis and IBD mucosa, we tested the possibility that Smad7 can negatively regulate Sirt1 expression." (PMID 30147698, 2018). "The importance of the i-Smad7 is underlined by observations that it is upregulated in inflammatory bowel diseases, and colitis in mice can be attenuated by antisense Smad7 oligonucleotides." (PMID 26617281, 2016). "Studies have shown that disruption of TGF-β1 signaling due to high levels of SMAD7 is a feature of colitis and blocking SMAD7 restores TGF- β1 signaling in colitis." (PMID 23560096, 2013). "Engineered CD4+ T cells with high expression of Smad7 have accelerated T cell proliferation and activation, resulting in severe colitis in the mouse." (PMID 22204639, 2011).
colitis (continued). "In line with the human data is the demonstration that Smad7 is over-expressed in the inflamed colon of mice with oxazolone-induced colitis and mice with trinitrobenzene sulfonic acid (TNBS)-induced colitis, two models showing some immunological similarities with UC and CD, respectively." (PMID 36714553, 2023). "Finally, intraperitoneal administration of Smad7 to mice attenuated DSS-driven colitis and increased TGF-β1 and PDL2/1-PD1 signaling." (PMID 36714553, 2023). "However, following administration of dextran sodium sulfate (DSS), which breaks the intestinal epithelial barrier thus allowing massive penetration of luminal antigens into the lamina propria, Smad7-Tg mice develop severe colitis compared to controls." (PMID 36714553, 2023). "Consistently, preclinical work in mouse models of IBD-like colitis showed that the knockdown of Smad7 with an antisense oligonucleotide (AS) attenuated the mucosal inflammation, thus paving the way for the development of an AS-containing pharmaceutical compound, named mongersen, for clinical use." (PMID 36678723, 2022). "Similarly, colitic mice intraperitoneally given Smad7 AS exhibit attenuation of DSS-induced colitis and increased TGF-β1 and PDL2/1-PD1 signaling." (PMID 33920230, 2021). "Smad7 is also over-expressed in other inflammatory disorders of the gut, such as refractory celiac disease, necrotizing enterocolitis and cytomegalovirus-induced colitis, even though evidence is still scarce and mainly descriptive." (PMID 33920230, 2021). "As pointed-out above, Smad7 is also over-expressed in IBD and CAC, and studies with Smad7-over-expressing mice would seem to suggest an anti-neoplastic effect of Smad7 on this type of neoplasia, as these animals develop more colitis but are resistant to experimental CAC than wild-type mice." (PMID 31052449, 2019). "If this comes to be true, we can speculate that Smad7 knockdown could notonly reduce colitis but also limit the occurrence of CAC." (PMID 31052449, 2019). "However, histological analysis of colonic sections revealed that Smad7 Tg mice developed a more severe colitis in comparison to WT mice." (PMID 30147698, 2018). "Finally, we showed that Smad7 Tg mice develop a more severe colitis in comparison to wild-type mice after DSS administration." (PMID 29973939, 2018). "Furthermore, SMAD7-overexpressing T cells enhanced development of colitis in a RAG adoptive transfer model of colitis even in the presence of co-transferred T regulatory cells." (PMID 29910812, 2018). "Interestingly, SMAD7 is overexpressed in the inflamed mucosa of IBD patients and targeting of SMAD7 has shown efficacy in mouse models of colitis, while ITGB1 single nucleotide polymorphisms have been identified as a risk factor in IBD." (PMID 24062740, 2013). "This seemingly paradoxical increase in the anti-inflammatory TGF-β in DSS-induced colitis may be due to overexpression of SMAD7, which negatively regulated TGF-β signaling by competing for SMAD3’s binding site on the TGF-β receptor, thereby blocking SMAD3 activation." (PMID 33859564, 2021). "Knockdown of Smad7, in fact, restores TGF-β1 activity, thus suppressing inflammatory cytokines release and leading to the resolution of colitis in mice." (PMID 33670735, 2021). "In patients with Crohn’s disease and patients with ulcerative colitis, the major human inflammatory bowel diseases (IBD), and in mice with IBD-like colitis, there is defective TGF-β1/Smad signaling due to high levels of the intracellular inhibitor Smad7." (PMID 33920230, 2021). "In this context, however, Garo and colleagues recently showed that specific deletion of Smad7 in DCs, as well as in CD4+ T cells, enhances TGF-β1 responsiveness and attenuates experimental colitis in mice." (PMID 33920230, 2021). "SMAD7 gene silencing, indeed, restored TGF-β1 activity, thus blocking inflammatory cytokines release and resolving the colitis in mice." (PMID 33801157, 2021).
colitis (continued). "To further assess the impact of Smad7 inhibition on the development of intestinal fibrosis, we used a mouse model of TNBS-mediated colitis-driven intestinal fibrosis." (PMID 29973939, 2018). "Consistently, mucosal T cells of Smad7-transgenic mice contained reduced levels of Sirt1, a defect that was amplified by induction of DSS colitis." (PMID 30147698, 2018). "In fact, SMAD7 restricts PD‐1‐induced regulatory T‐cell (Treg) differentiation and limits responses from T cells to TGF‐β, which further result in increased intestinal inflammation and progression of colitis." (PMID 36625080, 2023). "Up-regulation of Smad7 and reduced TGF-β1 signaling occurs also in necrotizing enterocolitis, environmental enteropathy, refractory celiac disease, and cytomegalovirus-induced colitis." (PMID 36714553, 2023). "In the T cell transfer colitis model, AhR activation ameliorates the course of colitis induced by wild-type T cells but does not influence colitis induced by Smad7 Tg T cells." (PMID 33920230, 2021). "It was reported that in comparison to the nontransgenic control mice, Smad7 overexpression increased the severity of colitis and reduced the incidence of tumors." (PMID 34059951, 2021). "Smad7 suppression by antisense oligonucleotide restored TGF-beta intracellular signaling in target cells, leading to resolution of the inflammatory process in animal models of colitis." (PMID 30979024, 2019). "Blockade of SMAD7 activity with an anti-sense oligonucleotide enhanced SMAD2 activation and reduced inflammatory cytokine production in intestinal explants and severity of colitis in mice sensitized and treated with TNBS or oxazolone." (PMID 29910812, 2018). "In the T-cell transfer colitis model, AhR activation significantly ameliorates the course of colitis driven by wild-type T cells, but does not influence colitis induced by Smad7 transgenic T cells." (PMID 29973939, 2018). "The authors showed that the absence of Smad7 attenuated colitis but increased fibrosis." (PMID 36714553, 2023). "Consistently, in the T-cell transfer colitis model, treatment of colitic mice with AhR activators attenuates the mucosal inflammation induced by wild-type T cells but does not influence colitis induced by Smad7 Tg T cells." (PMID 36714553, 2023). "Knockdown of Smad7 with a specific antisense oligonucleotide (ASO) restored the ability of TGF-β1 to hamper the production of inflammatory cytokines in CD mucosal cells and attenuated 2,4,6-trinitrobenzene sulfonic acid (TNBS)-driven experimental colitis (mimicking human CD) in mice." (PMID 33375423, 2020). "We generated a T cell-specific Smad7 transgenic (Tg) mouse on C57B6 genetic background, which does not develop spontaneously colitis." (PMID 29973939, 2018). "Moreover, by using the T cell-transfer model of colitis, we showed that the adoptive transfer of Smad7 Tg naïve CD4+ T cells, in the absence of Tregs, into naïve mice induces colitis that is more severe than that documented in mice reconstituted with wild-type T cells." (PMID 36714553, 2023). "Moreover, by using the T cell transfer model of colitis, it has been shown that the adoptive transfer of Smad7 Tg naïve CD4+ T cells, in the absence of Tregs, into naïve mice induces a colitis that is more severe than that documented in mice reconstituted with wild-type T cells." (PMID 33920230, 2021).
inflammatory bowel disease (30 papers, 2006 to 2023). A spectrum of small and large bowel inflammatory diseases of unknown etiology. "In several inflammatory diseases, like inflammatory bowel disease, celiac disease and kidney inflammation, high expression of Smad7 is associated with increased disease severity." (PMID 31698731, 2019). "Overexpression of Smad7 in intestinal macrophages is associated with their pro-inflammatory activation, and shRNA-mediated knockdown of Smad7 is currently being tested as a therapy for inflammatory bowel disease." (PMID 31698731, 2019). "Several IEC signature TFs have known associations with human Inflammatory Bowel Diseases (IBD), including SMAD7, CEBPG, STAT3, XBP1, HNF4A, ELF3, IRF1, and NFκB components IKBKB, IKBKG, and NFKBIZ." (PMID 28850571, 2017). "In contrast, because TGFβ is a potent immune suppressant in the gut, high levels of Smad7 expression in the gut cause inflammatory bowel disease (IBD) due to the loss of TGFβ responsiveness." (PMID 25566830, 2015). "Recently, SMAD family member 7 (Smad7) has attracted considerable attention in inflammatory diseases, including inflammatory bowel diseases (IBDs), as an inhibitor of transforming growth factor β (TGF-β)." (PMID 37507781, 2023). "To date, the effects of Smad7 have been extensively studied in inflammatory bowel diseases and tumour cells, but its role in vascular cells and atherosclerosis is still unclear." (PMID 33282009, 2020). "Specifically, we detected a reduced number of Smad7-expressing CD4+T lymphocytes in the colonic mucosa of inflammatory bowel disease patients who developed CAC compared to patients with uncomplicated disease." (PMID 33375423, 2020). "On the other hand, there is evidence that over-expression of Smad7 in immune cells infiltrating the inflamed gut of patients with inflammatory bowel disease can elicit anti-tumor responses, with the down-stream effect of attenuating CRC cell growth." (PMID 31052449, 2019). "The aberrant expression of SMAD7 has been shown to be involved in inflammatory bowel disease and scleroderma." (PMID 25295107, 2014). "Decreased expression of Smad7 has been reported in patients with scleroderma and inflammatory bowel disease." (PMID 22876112, 2012). "Firstly, dysregulation of Smad7 has been demonstrated to be associated with the pathogenesis of many human diseases, including malignancy, scleroderma, and chronic inflammatory bowel disease (IBD)." (PMID 22204639, 2011). "In addition, SMAD family member 7 (Smad7) has been confirmed to play vital roles in the pathogenesis and treatment of inflammatory diseases, such as inflammatory bowel disease." (PMID 37507781, 2023). "The investigation of SMAD family member 7 (Smad7) ASOs as a potential treatment for inflammatory bowel disease by inhibition of transforming growth factor-β1, which plays a role in mucosal inflammation in the gut, Smad7 ASOs were found safe and tolerable by patients with Crohn’s disease." (PMID 38203317, 2023). "Furthermore, in patients with inflammatory bowel disease and high concentrations of SMAD7 in the intestine, an antisense RNA has proven successful against SMAD7." (PMID 31968593, 2020). "Not only has inflammatory bowel disease (IBD) been associated with high SMAD7 levels, but studies have also asserted that knocking out SMAD7 in animals and pharmacologically blocking it in clinical studies can lead to reduced gut inflammation and improvement in symptoms." (PMID 29415065, 2018). "Interestingly, in inflammatory bowel disease, silencing of SMAD7 with anti-sense oligonucleotide treatment restored SMAD3 activation and reduced synthesis of inflammatory cytokines by endogenous TGFβ." (PMID 27473228, 2016). "Smad7 is a negative regulator of TGF-ß signaling and seems to be involved in pathogenesis of inflammatory bowel diseases (IBDs), including Crohn’s disease (CD) and ulcerative colitis (UC) and mediates intestinal inflammation." (PMID 37061565, 2023).
inflammatory bowel disease (continued). "In Crohn’s disease (CD), one of the major inflammatory bowel disease (IBD) in human beings, there is over-expression of Smad7, an intracellular inhibitor of the suppressive cytokine TGF-β1." (PMID 33076905, 2020). "Silencing SMAD7 can restore TGFβ/SMAD3 signaling and result in the suppression of inflammatory cytokine production in patients with inflammatory bowel diseases." (PMID 26446848, 2015). "Inhibiting Smad7 can restore the TGF-β1/Smad3 signaling and result in the suppression of inflammatory cytokine production in patients with inflammatory bowel diseases." (PMID 22429929, 2012). "In patients with inflammatory bowel diseases (IBD), there is defective TGF-β1/Smad signaling due to high Smad7, an inhibitor of TGF-β1 activity." (PMID 29973939, 2018). "Specifically in the cases of inflammatory bowel disease (IBD) and refractory celiac disease (RCD), SMAD7’s role in maintaining intestinal inflammation has been clearly established." (PMID 29415065, 2018). "On the other hand, Smad7 is over-expressed and limits TGF-β-mediated anti-inflammatory signals during inflammation of the central nervous system, in inflammatory bowel diseases (IBD), such as ulcerative colitis and Crohn’s disease, as well as in Helicobacter-pylori-related gastritis." (PMID 24317436, 2013).